ENSG00000267179 (novel protein)
Gene: Protein-coding gene on chromosome 19 (11,925,075 to 11,979,290, forward strand). Ensembl gene ENSG00000267179.
Genetic constraint (gnomAD): Loss-of-function variants: 33 observed, 40.32 expected, observed/expected ratio (o/e) 0.82, 90% interval 0.62 to 1.09. Missense variants: 447 observed, 520.83 expected, observed/expected ratio (o/e) 0.86, 90% interval 0.79 to 0.93. Synonymous variants: 166 observed, 177.3 expected, observed/expected ratio (o/e) 0.94, 90% interval 0.82 to 1.07.